GCNT2 (glucosaminyl (N-acetyl) transferase 2 (I blood group))
Diseases named in the same sentence as GCNT2 in open-access papers (continued):
Sharing a sentence is not in itself a finding about the gene and the disease.
melanoma (continued). "Analyses of two representative N-glycosylated protein families, insulin-like growth factor-1 receptor (IGF1R) and integrins, revealed that GCNT2/I-branched glycan modifications inhibited IGF-1 and ECM-mediated melanoma cell proliferation, survival, and associated downstream signaling pathways." (PMID 30135430, 2018). "Hence, the decrease in GCNT2 and increase in i-linear glycan expression on melanoma cells reflect a more dedifferentiated state compared to their normal counterpart." (PMID 30135430, 2018). "Because GCNT2 modifies polyLacNAcs, we hypothesized that GCNT2/I-branched glycans may control Gal-1- and/or Gal-3-binding in melanoma cells, thereby regulating downstream IGF1R and integrin-mediated signaling pathways." (PMID 30135430, 2018). "Furthermore, utilizing an anchorage-independent growth assay designed to study tumorigenicity and survival of malignant cells, we found that melanoma cells expressing GCNT2/I-branched glycans formed smaller and fewer colonies." (PMID 30135430, 2018). "Therefore, a more complete delineation of GCNT2 glycoprotein targets in melanoma cells is needed, as this should help to further define the role of the glycome in malignancy." (PMID 30135430, 2018). "In addition, GCNT2/I-branched glycan expressing melanoma cells displayed higher levels of proapoptotic genes, BID and BAX, and had lower expression of prosurvival genes, BCL-2 and BCL-XL." (PMID 30135430, 2018). "Furthermore, these data demonstrate that I-branch modifications to N-glycans by GCNT2 can lead to a global change in cell surface glycosylation that significantly alters melanoma cell growth, survival, and various signaling pathways." (PMID 30135430, 2018). "Furthermore, data mining of publicly available datasets from three independent clinical cohorts, consistently confirmed lower GCNT2 mRNA levels in clinical melanoma specimens compared to normal melanocytes." (PMID 30135430, 2018). "With this observation, we sought to determine whether differential GCNT2/I-branched glycan expression regulates melanoma growth and survival, in part, through IGF1R and/or through integrin-mediated pathways." (PMID 30135430, 2018). "Functionally, we found that knockdown of GCNT2 significantly enhanced melanoma xenograft growth and three-dimensional colony formation and survival, whereas enforced expression of GCNT2 significantly decreased melanoma xenograft growth, and inhibited three-dimensional colony formation and survival." (PMID 30135430, 2018). "Interestingly, we did not observe a significant difference in either α2,6 (SNA lectin) or α2,3 (MAL-II lectin) sialic acid content in GCNT2 KD, GCNT2 OE, or control melanoma cell lines." (PMID 30135430, 2018). "The negative association of GCNT2 with metastasis suggests that loss of GCNT2/I-branched glycans may help melanomas progress." (PMID 30135430, 2018). "Moreover, we found that GCNT2/I-branched glycans decreased IGF-1 and RGD ligand binding activity on melanoma cells, suggesting that GCNT2/I-branches may modulate IGF1R and fibronectin: integrin signaling through modulation of ligand binding capacity." (PMID 30135430, 2018). "Thus, we sought to determine whether GCNT2/I-branched glycans regulate growth factor receptor and/or integrin-mediated melanoma cell growth and survival." (PMID 30135430, 2018). "Altogether, these data suggest that GCNT2/I-branched glycans regulate IGF1R and integrin growth and survival pathways in melanoma cells." (PMID 30135430, 2018). "To dissect how differential GCNT2/I-branched glycan expression modulates IGF1R and integrin activities in melanoma cells, we analyzed related signaling events." (PMID 30135430, 2018). "Together, these data suggest that GCNT2/I-branch expression modulates IGF-1 and RGD binding activity on melanoma cells to potentially regulate IGF1R- and integrin-related signaling." (PMID 30135430, 2018).
melanoma (continued). "Given its importance in melanoma progression, we explored whether Gal-3 across various concentrations (0.02, 0.1, 0.5, and 1 μg/mL) influences this pathway and how its effects differ in the presence or absence of GCNT2/I-branching." (PMID 40430022, 2025). "Thus, while GCNT2/I-branched glycans decrease Gal-3-binding, we do not believe that this inhibition is responsible for mediating the observed reduction in IGF1R and integrin signaling in melanoma cells." (PMID 30135430, 2018).
colon cancer (6 papers, 2014 to 2025). "AQP1, a Colton blood group antigen system gene, was reported to be associated with poor prognosis in colon cancer and lung adenocarcinoma, while seven of the fifteen genes were reported to be prognostic in one tumor type (GCNT2, FUT7, FUT3, FUT2, DARC, CR1 and BSG)." (PMID 35955933, 2022). "For example, high expression level of GCNT2 and its I-branched glycan product was proved to accelerate epithelial-to-mesenchymal transition in colon cancer." (PMID 36611197, 2023). "In malignant colon tumors, high levels of GCNT2 transcripts are found in invasive cells emerging from hypoxic regions." (PMID 24753248, 2014).
cataract (4 papers, 2012 to 2017). Partial or complete opacity of the crystalline lens of one or both eyes that decreases visual acuity and eventually results in blindness. "Recessive mutations in GCNT2 are known to cause an adult i blood group phenotype with congenital cataracts in some cases." (PMID 27609212, 2016). "Here, we report a novel insertion/deletion mutation at the GCNT2 locus that is responsible for congenital cataracts in a large consanguineous family." (PMID 27936067, 2016). "Here, we report a novel deletion in GCNT2 that causes autosomal recessive congenital cataracts." (PMID 27936067, 2016).
congenital cataracts (3 papers, 2016 to 2025). "The lost function of GCNT2 due to the gene mutation was associated with adult i blood group phenotype as well as congenital cataracts." (PMID 40034691, 2025). "It has been reported that genetic mutation of GCNT2, leading to loss of GCNT2 expression, was responsible for the disease of adult i phenotype and congenital cataracts." (PMID 40034691, 2025). "Recessive mutations in GCNT2 result in an adult i blood group phenotype, which is also associated with congenital cataracts in some cases." (PMID 27609212, 2016). "Annotations for Gcnt2 dysfunction mainly involve congenital cataracts." (PMID 35812759, 2022). "We identified a ~98-kb homozygous deletion involving several exons of GCNT2 and the region upstream of TFAP2A in two children affected with congenital cataracts from a consanguineous family of Pakistani decent." (PMID 27609212, 2016).
lymph node metastasis (3 papers, 2021 to 2025). "The hypomethylation of GCNT2 has emerged as a potential biomarker linked to lymph node metastasis in CRC." (PMID 38255946, 2024). "Studies have reported that the diagnostic accuracy for predicting lymph node metastasis via GCNT2 hypomethylation in primary tumours was 86.2% which is higher than the diagnostic accuracies of CT (59.38%) and MRI (84%) methods used to predict lymph node metastasis in CRC." (PMID 38255946, 2024). "Other EMT-related genes with prognostic value are represented by GCNT2, retrieved in the literature as methylated, correlated with lymph node metastasis of colorectal cancer." (PMID 34073426, 2021).
prostate carcinoma (3 papers, 2018 to 2025). A carcinoma that arises from epithelial cells of the prostate gland. "FUT1 and one of GCNT1, GCNT2 or GCNT 3 are essential enzymes for F77-specific O-linked glycosylation in prostate cancer cells." (PMID 29423071, 2018).
breast tumor (2 papers, 2013 to 2023). "Using data from The Cancer Genome Atlas, we found that the A allele of rs9348512 was strongly associated with mRNA levels of GCNT2 in breast tumors (p = 7.3×10−5)." (PMID 23544012, 2013).
esophageal squamous cell carcinoma (2 papers, 2021 to 2024). Esophageal squamous cell carcinoma (ESCC) is a type of esophageal carcinoma (EC) that can affect any part of the esophagus, but is usually located in the upper or middle third. "Gcnt2 has been found to induce epithelial-mesenchymal transition and enhance migration and invasion of esophageal squamous cell carcinoma cells." (PMID 38770735, 2024).
leukemia (2 papers, 2023 to 2025). A malignant (clonal) hematologic disorder, involving hematopoietic stem cells and characterized by the presence of primitive or atypical myeloid or lymphoid cells in the bone marrow and the blood. "Importantly, many studies have pointed out that the high level of I-antigen synthesized by GCNT2 could increase the susceptibility of malignant cells against immune cells in leukemia." (PMID 36611197, 2023).
lung adenocarcinoma (2 papers, 2022 to 2025). A carcinoma that arises from the lung and is characterized by the presence of malignant glandular epithelial cells. "Trajectory analysis identified ERBB4, SEMA4A, GCNT2 and SOX4 as key factors in AT2 cells that may promote cell proliferation, migration, or epithelial-mesenchymal transition (EMT) during the progression of lung adenocarcinoma (LUAD)." (PMID 41415280, 2025).
lung carcinoma (2 papers, 2015 to 2022). "Interestingly, GCNT2 overexpression has been linked to breast and lung cancer metastasis." (PMID 25578962, 2015). "So GCNT2 may be a novel gene contributing to metastasis with preferential expression in lung cancer." (PMID 35780128, 2022).
allergic disease (1 paper, 2025). An immune response that occurs following re-exposure to an innocuous antigen, and that requires the presence of existing antibodies against that antigen. "This clearly highlights that GCNT2 plays a role in allergic diseases." (PMID 41065049, 2025). "Several studies have investigated the mechanistic function of GCNT2 in different immune cells, which could explain the impact on allergic diseases." (PMID 41065049, 2025).
autism (1 paper, 2009). Persistent deficits in social interaction and communication and interaction as well as a markedly restricted repertoire of activity and interest as well as repetitive patterns of behavior. "Gene-network analysis of the genes highlighted by Prioritizer in the non-complex-autism group revealed a putative gene-network in four CNVs containing genes known to operate in glycobiology (B3GALT6, GCNT2, LARGE, and GALNT9)." (PMID 19492091, 2009).
bladder cancer (1 paper, 2025). "To verify this, we aimed to explore the associations between GCNT2 expression and clinical features of patients with bladder cancer in this study." (PMID 40149658, 2025). "Our findings provide insights into the tumor–immune interactions in bladder cancer and GCNT2 and its associated pathways as potential targets for novel immunotherapeutic strategies." (PMID 40149658, 2025). "Notably, GCNT2 overexpression enhanced the susceptibility of bladder cancer cells to NK cell-mediated killing, whereas its knockdown promoted immune evasion." (PMID 40149658, 2025). "We found an inverse correlation between GCNT2 expression in bladder cancer specimens obtained via transurethral resection of bladder tumor (TURBT) and cancer aggressiveness." (PMID 40149658, 2025). "We examined GCNT2, an enzyme crucial for blood group I antigen formation, to verify its correlation with bladder cancer aggressiveness." (PMID 40149658, 2025). "In this study, we investigated the roles of glucosaminyl (N-acetyl) transferase 2 (GCNT2) in bladder cancer progression and immune evasion." (PMID 40149658, 2025). "Our findings indicate the crucial roles of GCNT2 in bladder cancer malignancy." (PMID 40149658, 2025). "Because tumor invasiveness also regulates tumor malignancy, we tested whether GCNT2 regulates bladder cancer invasiveness." (PMID 40149658, 2025). "To determine whether GCNT2 expression affects the NK cell–bladder cancer cell interactions, we compared NK immunity evasion between normal and GCNT2-overexpressing bladder cancer cells." (PMID 40149658, 2025). "Our data revealed that GCNT2 downregulation was beneficial for bladder cancer aggressiveness." (PMID 40149658, 2025). "Considering the crucial roles of GCNT2 in glycan branching, we hypothesized that it affects the tumor cell dynamics, particularly in bladder cancer, in which cell surface glycosylation patterns are critical for tumor proliferation and invasion." (PMID 40149658, 2025). "Furthermore, GCNT2 overexpression in bladder cancer cells strongly stimulated the natural killer (NK) cell functions." (PMID 40149658, 2025). "Moreover, GCNT2 levels corresponded to the presence of I-antigen on the surfaces of bladder cancer cells." (PMID 40149658, 2025). "Therefore, we confirmed that GCNT2 acts on glycans in bladder cancer cells." (PMID 40149658, 2025). "qPCR analysis of bladder cancer cell lines revealed high GCNT2 levels in the non-invasive KK47 cells and low GCNT2 levels in the muscle-invasive T24 and YTS-1 cells." (PMID 40149658, 2025). "Our results suggest that GCNT2 does not affect integrin-mediated pathways in bladder cancer cells at least, since the expression level of GCNT2 did not affect cell invasiveness or intercellular adhesion, which are likely to be mediated by integrins." (PMID 40149658, 2025).
bladder tumors (1 paper, 2025). "Therefore, bladder tumors with low GCNT2 expression possibly develop highly malignant properties due to alterations in their cell surface carbohydrates." (PMID 40149658, 2025).
hyperandrogenism (1 paper, 2025). Excessive secretion of androgens from the adrenal glands or gonads. "This regulatory axis not only underscores the pathophysiological links between hyperandrogenism and metabolic dysfunction but also positions GCNT2 as a potential therapeutic target for restoring metabolic balance." (PMID 40375948, 2025).
hyperferritinemia (1 paper, 2011). "In the family with the “ii” blood group we found a novel GCNT2 mutation c.G935A (p.G312D) in the cataract patients, while in the family with hyperferritinemia cataract syndrome we identified a G→C heterozygous mutation at position +32 of FTL." (PMID 21541272, 2011).
Infertility (1 paper, 2025). "Studies have indicated that alterations in GCNT2 expression can lead to changes in SHBG levels, further implicating GCNT2 in the pathophysiology of PCOS and its associated symptoms, such as insulin resistance and infertility." (PMID 40375948, 2025).
Insulin resistance (1 paper, 2025). Increased resistance towards insulin, that is, diminished effectiveness of insulin in reducing blood glucose levels. "By influencing the PI3K/Akt pathway via N-glycosylation, GCNT2 serves as a critical mediator that not only affects androgen levels but also addresses the underlying insulin resistance that characterizes the syndrome." (PMID 40375948, 2025).
metastatic disease (1 paper, 2018). "As such, detection of GCNT2/I-branched glycans provides intriguing insights into its potential use as a biomarker to help predict which patients are at risk for progression to metastatic disease." (PMID 30135430, 2018).
osteoarthritis (1 paper, 2024). A noninflammatory degenerative joint disease occurring chiefly in older persons, characterized by degeneration of the articular cartilage, hypertrophy of bone at the margins and changes in the synovial membrane. "In conclusion, we found that miR-199b-5p is elevated in osteoarthritis and may affect cell viability and related cytokines by potentially targeting Gcnt2 and Fzd6." (PMID 38770735, 2024).
respiratory allergy (1 paper, 2025). "Furthermore, GCNT2 was hypermethylated in a study investigating DNA methylation of 11‐year‐old patients with respiratory allergy compared to healthy controls, albeit it was not indicated which CpG positions were affected." (PMID 41065049, 2025).
tumor (15 papers, 2012 to 2025). "An emerging glycosyltransferase GCNT2, which catalyzes I-branched N-glycans, was documented to be associated with various cancers, acting as an oncogene or a tumor suppressor in different cancer types." (PMID 40034691, 2025). "In the tumor, aberrant GCNT2 methylation was closely associated with tumor development by controlling GCNT2 expression." (PMID 40034691, 2025). "Hypomethylation of GCNT2 leading to upregulation, that associated with tumor initiation, development, and metastasis, has been demonstrated in several malignancies." (PMID 40034691, 2025). "Therefore, in these cancer types, increased GCNT2 expression is associated with tumor cell invasiveness and malignancy." (PMID 40149658, 2025). "Low GCNT2 levels were associated with advanced tumor stage and grade, suggesting the tumor-suppressive roles of GCNT2." (PMID 40149658, 2025). "A similar situation has been observed in CRC, where reduced GCNT2 was found in primary tumor tissues compared to corresponding normal mucosa, however, DNA hypomethylation inducing GCNT2 expression enhanced progression and led to poor survival." (PMID 40034691, 2025). "The function of GCNT2 has been documented to act as an oncogenic driver or tumor suppressor in different types of tumor, but the role of GCNT2 and the epigenetic regulation mechanism in AML, however, has not yet been clarified." (PMID 40034691, 2025). "Hypoxia triggers glycan changes in tumor-initiating cells (TICs) and metastatic melanoma (MM) cells, such as the activation of Gal-8 and the reduction of the I-branching enzyme β1,6 N-acetylglucosaminyltransferase 2 (GCNT2)." (PMID 40134029, 2025). "Silencing GCNT2 increases TIC marker levels and tumor initiation potential in vivo." (PMID 40134029, 2025). "The qPCR results confirmed the upregulation of Coro7 (p = 0.04), Ccl4 (non-significant) and Gcnt2 (p = 0.011) in the caerin treated tumour bearing mice when compared to untreated mice." (PMID 36497272, 2022). "Certain target genes (e.g., ERBB4, SEMA4A, GCNT2 and SOX4) play critical roles in shaping two pathways related to the malignant fate of AT2 cells, which are inseparable from tumor differentiation and migration, suggesting that these genes may be novel therapeutic targets for further studies." (PMID 41415280, 2025). "FUT1, FUT2, B3GNT2, GCNT2, and ST8SIA5 are involved in the blood group biosynthesis, a synthesis of blood group antigens process, which are glycan structures on cell surfaces that can influence tumour cell interactions with the TME, including immune system components." (PMID 39457550, 2024). "Interestingly, the level of GCNT2 hypomethylation was found to be similar between the tumour tissues and their corresponding normal tissues, suggesting the potential use of GCNT2 hypomethylation in normal mucosa tissue to predict lymph node metastasis in CRC patients." (PMID 38255946, 2024).